KCNQ2 (potassium voltage-gated channel subfamily Q member 2)
Diseases named in the same sentence as KCNQ2 in open-access papers (continued):
Sharing a sentence is not in itself a finding about the gene and the disease.
developmental delay (14 papers, 2015 to 2025). "In summary, this study combined clinical analysis and functional characterization to investigate a group of patients carrying pathogenic KCNQ2 variants who exhibited neonatal epileptic onset and developmental delay ranging from moderate to profound." (PMID 37497102, 2023). "De novo heterozygous mutations in KCNQ2 genes are associated with early-onset epileptic encephalopathy and neurodevelopmental disorders including developmental delay and intellectual disability." (PMID 35645364, 2022). "Patients with de novo mutations and KCNQ2 EE are associated with severe developmental delays." (PMID 35269516, 2022). "In our cohort, several genes were frequently implicated in cases of genetic epilepsy and developmental delay, including PRRT2 (n:2), KCNQ2 (n:2), SCN1A (n:2), PLA2G6 (n:2), and KDM6A (n:2)." (PMID 40083435, 2025). "In the previous study, the recurrent KCNQ2 variant R198Q is associated with stereotypes with refractory seizures, severely abnormal VEEG and developmental delay." (PMID 34163418, 2021). "GoF variants in KCNQ2 and KCNQ3 genes were recently reported to cause profound developmental delay, neonatal non-epileptic myoclonus, and later-onset epilepsy such as infantile spasms or the autism phenotype with no clinical seizures, respectively." (PMID 39175503, 2024).
Ohtahara syndrome (13 papers, 2013 to 2022). "Recent studies have identified that de novo mutations in helices A and B of KCNQ2 are associated with neonatal epileptic encephalopathy including drug-resistant Ohtahara syndrome." (PMID 25077630, 2014). "In addition, KCNQ2 mutations have been found in a few patients with refractory neonatal seizures similar to the Ohtahara syndrome." (PMID 25566516, 2014). "Similar to the KCNQ2 variants, GoF SCN2A variants can also cause a spectrum of intractable childhood epilepsies ranging from Ohtahara syndrome and migrating focal seizures to epileptic spasms and Dravet syndrome." (PMID 34356067, 2021). "In addition, mutations of KCNQ2 are known to cause not only benign epilepsy, but also malignant phenotypes, e.g., EOEE and Ohtahara syndrome, for which treatments based on an understanding of the underlying pathomechanisms are urgently required." (PMID 26910900, 2016).
Dravet syndrome (12 papers, 2015 to 2025). "For example, mutations in the SCN1A gene are associated with Dravet syndrome, while mutations in the KCNQ2 and KCNQ3 genes are linked to benign familial neonatal epilepsy (BFNE)." (PMID 37927689, 2023). "For example, SCN1A mutations are linked to Dravet syndrome, while mutations in KCNQ2 and KCNQ3 are associated with benign familial neonatal epilepsy." (PMID 37927689, 2023). "For instance, the Othahara syndrome could be due to mutations in the KCNQ2 and SCN2A genes and the Dravet Syndrome could be due to mutations in the SCN1A, SCN2A, SCN1B genes." (PMID 31907053, 2020). "Besides the six patients with SCN1A variants who could all be classified as having Dravet syndrome, large phenotypic heterogeneity was noted among patients with PRRT2, KCNQ2, and SCN2A variants." (PMID 31572294, 2019). "Efficacy of the KD, with greater than 90% seizure reduction, has been reported in patients with monogenic DEEs, including KCNQ2-DEE and Dravet syndrome." (PMID 33013448, 2020). "Recent surveys show no instances of SUDEP among human KCNQ2 DEE cohorts, in contrast to Dravet syndrome, which has high SUDEP risk." (PMID 38260608, 2024).
Intellectual disability (12 papers, 2014 to 2025). "In summary, the pathogenic variants of KCNQ2 have been observed in neonatal developmental epileptic encephalopathy, refractory epilepsy, and intellectual disability." (PMID 40342533, 2025). "However, it is interesting to note that patients with the KCNQ2-E515D variant may exhibit a higher rate of intellectual disability than BFNE patients with other KCNQ2 variants." (PMID 28686619, 2017).
infantile epileptic encephalopathy (10 papers, 2016 to 2026). an epileptic condition characterized by epileptiform abnormalities associated with progressive cerebral dysfunction. "We hypothesize that the mechanisms of early infantile epileptic encephalopathy–causative GOF associated with KCNQ2–R201C likely includes supertrafficking." (PMID 33600800, 2021). "In this regard, we noted that one of the neuronal paralogs of KCNQ1, KCNQ2, is known to be subject to GOF mutations that cause a severe disease, early infantile epileptic encephalopathy." (PMID 33600800, 2021).
bipolar disorder (8 papers, 2010 to 2023). A disorder of the brain that causes unusual shifts in mood, energy, activity levels and the ability to carry out day-to-day tasks. "Furthermore, some interactions between SNPs in association with bipolar disorder were described in a discovery GWAS dataset, of which the most significant ones were SNPs from KCNQ2 with SNPs from ANK3." (PMID 32120974, 2020). "Recent studies have shown that both the KCNQ2 channel mutants—associated with bipolar disorder—and wild-type KCNQ2 channels are phosphorylated by GSK-3β in vitro, at a site that requires PKA priming and is dephosphorylated by protein phosphatase 2A (PP2A; also known as calcineurin)." (PMID 22811658, 2012). "KCNQ5 (potassium voltage-gated channel subfamily KQT member 5) may contribute to episodic disturbances of mood and behavior as well-characterized roles in other ion-channelopathies, and two family members, KCNC2 and KCNQ2, were found to be associated with bipolar disorder." (PMID 20808825, 2010). "One additional study showed that the interaction of potassium channel genes ANK3 and KCNQ2 were also related to bipolar disorder." (PMID 37161899, 2023).
autism (7 papers, 2015 to 2024). Persistent deficits in social interaction and communication and interaction as well as a markedly restricted repertoire of activity and interest as well as repetitive patterns of behavior. "Thus, alterations of KCNQ2 have been associated with seizures, autism as well as cognitive and developmental disabilities." (PMID 38318351, 2024). "MEAs have been deployed to investigate gene mutations associated with monogenic forms of autism in hiPSC-neurons such as CNTN5, EHMT2, KCNQ2, ATRX, and SCN2A." (PMID 37441676, 2023).
Tinnitus (7 papers, 2014 to 2024). Tinnitus is an auditory perception that can be described as the experience of sound, in the ear or in the head, in the absence of external acoustic stimulation. "In contrast, non-tinnitus mice are associated with normal KCNQ2/3 channel activity and normal spontaneous firing rates of fusiform cell." (PMID 26312501, 2015). "Reduction of KCNQ2/3 currents is associated with increased spontaneous firing rate and tinnitus behavior 7 days after noise exposure." (PMID 26312501, 2015). "The ability of KCNQ channel activators to prevent the development of tinnitus is probably occurring through the reversal of the pathogenic reduction of KCNQ2/3 channel activity and the promotion of the natural resilience to tinnitus." (PMID 26312501, 2015). "Our results highlight that pathogenic (reduction) and homeostatic plasticity (recovery) in KCNQ2/3 channel activity are associated with tinnitus and non-tinnitus behavior, respectively." (PMID 26312501, 2015). "We conclude that reduction in KCNQ2/3 channel activity is a robust mechanism for triggering tinnitus, but its pathogenic effect is gated by the RMP of fusiform cells." (PMID 26312501, 2015). "Importantly, fusiform cell hyperactivity in tinnitus mice is associated with reduced KCNQ2/3 currents at hyperpolarized membrane potentials, due to a depolarizing shift in the voltage dependence of KCNQ2/3 channel opening." (PMID 26312501, 2015). "In this study, we observed decreased latency of APs in pyramidal neurons in tinnitus animals, indicating KCNQ2 and KCNQ3 channel dysfunction." (PMID 39296986, 2024). "Numerous studies have attempted to utilize KCNQ2/3 channel activators, such as retigabine, or systemically administered newly synthesized molecules to alleviate tinnitus." (PMID 39296986, 2024). "Dysfunction of KCNQ2 and KCNQ3 channels—voltage-dependent potassium ion channels—in the cochlear nucleus can cause tinnitus." (PMID 39296986, 2024). "Application of retigabine at day 4 significantly reduced the percentage of mice that developed tinnitus (‘Materials and methods’), suggesting that the recovery of KCNQ2/3 currents between day 4 and 7 is crucial for tinnitus resilience." (PMID 26312501, 2015). "This novel finding suggests a temporal window during which endogenous, intrinsic mechanisms can restore KCNQ2/3 channel activity and lead to tinnitus resilience." (PMID 26312501, 2015). "Mice that show preservation of reduced KCNQ2/3 channel activity until 7 days post noise exposure show fusiform cell hyperactivity and develop tinnitus." (PMID 26312501, 2015). "Pharmacological activation of KCNQ channels by retigabine, an FDA approved anti-epileptic drug that activates KCNQ2-5, or by SF0034, a potent KCNQ2/3 activator, prevent seizures, neuropathic pain and the development of tinnitus." (PMID 26312501, 2015). "Resilience to tinnitus is developed in mice that show a re-emergence of KCNQ2/3 channel activity and a reduction in HCN channel activity." (PMID 26312501, 2015). "Inhibiting KCNQ2 expression abolished the therapeutic effect of infrared photons on tinnitus." (PMID 39296986, 2024). "We confirmed that KCNQ2 in the auditory cortex can alleviate tinnitus development and maintenance." (PMID 39296986, 2024). "However, in animals that successfully avoid developing tinnitus, KCNQ2/3 activity spontaneously recovers over the course of a few days." (PMID 26312501, 2015). "Elucidation of these mechanisms will unmask previously unknown plasticity mechanisms of KCNQ2/3 channel activity, and lead to new targets for drug development towards enhancing resilience to noise-induced tinnitus in humans." (PMID 26312501, 2015). "Given that fusiform cells from non-tinnitus mice display control-level KCNQ2/3 currents 7 days post noise exposure, our results suggest that it is the recovery in KCNQ2/3 channel activity, not the lack of reduction in KCNQ2/3 currents, which is linked with the resilience to tinnitus." (PMID 26312501, 2015).
Tinnitus (continued). "Furthermore, tinnitus-related behaviors exhibited alleviation upon exposure to infrared photons, which facilitate the generation of a K+ current due to the loosening of the KCNQ2 channel’s structure." (PMID 39296986, 2024). "Moreover, dysfunction of KCNQ2 and KCNQ3 channels in the cochlear nucleus can cause tinnitus." (PMID 39296986, 2024). "Therefore, besides targeting KCNQ2/3 channel activators for preventing tinnitus, manipulations that hyperpolarize the fusiform cell RMP may also provide additional therapeutic approaches." (PMID 26312501, 2015). "Similarly, because plasticity of multiple conductances is involved in tinnitus, we propose that a combination of drugs that enhance KCNQ2/3 and reduce HCN channel activity represents a potent therapeutic approach that will enhance resilience and reduce vulnerability to tinnitus." (PMID 26312501, 2015). "In this study, we explored the pathological roles of KCNQ2 and KCNQ3 channels in the auditory cortex in tinnitus development, emphasizing the crucial role of hyperexcitability of excitatory neurons." (PMID 39296986, 2024). "This study aimed to elucidate the pathological roles of KCNQ2 and KCNQ3 channels within the auditory cortex in tinnitus development and examine the therapeutic potential of mid-infrared photons for tinnitus treatment." (PMID 39296986, 2024). "Despite the recognized significance of KCNQ2 and KCNQ3 channels in the auditory cortex, their precise relationship and implications in the pathogenesis of tinnitus remain areas of scientific inquiry." (PMID 39296986, 2024). "Mice that show a natural recovery of KCNQ2/3 channel activity and a reduction in HCN channel activity display normal level of spontaneous firing rates and are resilient to tinnitus." (PMID 26312501, 2015). "Taken together, our results suggest that increases in KCNQ2/3 channel activity promote a decrease in fusiform cell HCN channel activity and resilience to tinnitus." (PMID 26312501, 2015). "Considering the strong correlation between AP latency and KCNQ2 and KCNQ3 channels, the observed shorter latency in the tinnitus group may be attributed to abnormal functioning or expression of KCNQ2 and KCNQ3 channels." (PMID 39296986, 2024). "Drugs that increase activity of KCNQ2/3 channels, and/or reduce activity of HCN channels, could thus boost resilience to tinnitus." (PMID 26312501, 2015). "Moreover, previous findings showed that in vivo pharmacological activation of KCNQ currents with either KCNQ2-5 or KCNQ2/3 channel activators, retigabine or SF0034, respectively, prevented the development of tinnitus." (PMID 26312501, 2015). "Our results highlight the importance of KCNQ2/3 and HCN channels in the resilience to tinnitus and illuminate therapeutic paths that may enhance resilience for tinnitus prevention." (PMID 26312501, 2015). "Our results highlight KCNQ2/3 and HCN channels as potential targets for designing novel therapeutics that may promote resilience to tinnitus." (PMID 26312501, 2015). "On the other hand, non-tinnitus mice do not show fusiform cell hyperactivity after sound exposure and express normal levels of KCNQ2/3 currents." (PMID 26312501, 2015). "Existing literature on KCNQ2 focused on tinnitus development, rather than treatment." (PMID 39296986, 2024). "However, the precise correlation between KCNQ2 and KCNQ3 channels within the auditory cortex and the etiology of tinnitus have not yet been fully elucidated." (PMID 39296986, 2024).
Ataxia (6 papers, 2015 to 2025). Ataxia refers to impaired coordination of voluntary muscle movement. "For instance, the mutated KCNQ2 and KCNQ3 genes, which encode Kv7.2 and Kv7.3, respectively, enable benign familial neonatal convulsions, and genetic suppression of small-conductance Ca2+-activated K+ channels (SK) in deep cerebellar neurons can result in ataxia." (PMID 36393851, 2022). "Thus, much like retigabine activation of KCNQ2/3, Kv1 current augmentation by small molecules such as gallic acid would be expected to dampen excess neural excitability and potentially ameliorate ataxia even if Kv1 channel dysfunction was not the original cause." (PMID 37280215, 2023).
Dystonia (6 papers, 2015 to 2025). An abnormally increased muscular tone that causes fixed abnormal postures. "It is already known that single gene disorders, including SCN1A, SCN2A, KCNQ2, PRRT2, and pyridoxine deficiency, can result in isolated dystonia; we add CdLS5 (HDAC8 variation) to this expanding spectrum." (PMID 38910710, 2024). "Since it is already known that single gene disorders, including SCN1A, SCN2A, KCNQ2, PRRT2, and pyridoxine deficiency, can result in isolated dystonia, we add CdLS5 (HDAC8 variation) to this expanding spectrum." (PMID 38910710, 2024).
infantile spasms (6 papers, 2014 to 2025). A rare epilepsy syndrome characterized by onset of epileptic spasms in infants between 2 and 12 months of age, and rarely up to 24 months. "Few reports have previously documented the development of KCNQ2-EOEE into West syndrome." (PMID 40342533, 2025). "Recently, GoF variants in the KCNQ2 gene were described, causing a distinct phenotype with profound developmental delay, neonatal non-epileptic myoclonus, and later onset epilepsy such as infantile spasms." (PMID 39175503, 2024). "When the gene was reported, the child was diagnosed with KCNQ2-EOEE,which later developed into West syndrome." (PMID 40342533, 2025).
epilepsy syndrome (5 papers, 2014 to 2025). A syndrome that has a characteristic cluster of clinical features and/or lectroencephalographic (EEG) findings that reflect underlying epileptic activity. "Of course, further investigations are needed to better understand the role of KCNQ2 in this epileptic syndrome." (PMID 39796146, 2024).
Myokymia (5 papers, 2014 to 2022). Myokymia consists of involuntary, fine, continuous, undulating contractions that spread across the affected striated muscle. "It has been reported that a KCNQ2 mutation (R207W) causes myokymia in human patients." (PMID 35858950, 2022). "Their enrichment at the axonal surface is impaired by mutations in KCNQ2 carboxy-terminal tail that cause benign familial neonatal convulsion and myokymia, suggesting that their correct surface distribution and density at the axon is crucial for control of neuronal excitability." (PMID 25077630, 2014). "Loss-of-function mutations in KCNQ2 and KCNQ3 channels occur in a small human population, causing a number of neurological disorders such as myokymia, neuromyotonia, neonatal-onset epilepsy, and epileptic encephalopathy." (PMID 35858950, 2022). "It would be interesting to investigate whether KCNQ2 activators and inhibitors may be used to treat myokymia, neuromyotonia, and other neuromuscular disorders." (PMID 35858950, 2022).
autism spectrum disorder (4 papers, 2022 to 2025). A spectrum of developmental disorders that includes autism, and Asperger syndrome. "This case report describes the clinical behavioral phenotype of a 6-year-old boy carrying a de novo heterozygous KCNQ2 mutation, affected by early-onset seizures and autism spectrum disorder (ASD)." (PMID 35645364, 2022). "Patients with KCNQ2 EE present with severe seizures that often remit as patients become older; however, such patients experience poor neurodevelopmental outcomes in terms of cognition, motor skills, and language, and they may also exhibit autistic spectrum disorder (ASD)." (PMID 35269516, 2022).